RNU6-980P (RNA, U6 small nuclear 980, pseudogene)
Gene: Small nuclear RNA gene on chromosome 19 (53,732,981 to 53,733,083, reverse strand). Ensembl gene ENSG00000252734.
Homologues: Orthologues: macaque U6 (86% identical), guinea pig U6 (75% identical). Paralogues in human: RNU6-1041P (83% identical), RNU6-982P (82% identical), RNU6-46P (80% identical), RNU6-1316P (79% identical), RNU6-40P (79% identical), RNU6-1145P (78% identical), RNU6-16P (78% identical), RNU6-38P (78% identical), RNU6-86P (78% identical), RNU6-1 (77% identical), RNU6-1036P (77% identical), RNU6-116P (77% identical), and 1285 more.